TLE1 (TLE family member 1, transcriptional corepressor)
Diseases named in the same sentence as TLE1 in open-access papers (continued):
Sharing a sentence is not in itself a finding about the gene and the disease.
synovial sarcoma (continued). "The mean sensitivity and specificity of TLE1 in detecting synovial sarcoma were 94% (95% CI 91%–97%) and 81% (95% CI 72%–91%), respectively, when all studies were aggregated together, regardless of the immunohistochemical grading system used to measure the marker's expression." (PMID 32322158, 2020). "TLE1 is a sensitive and specific marker for synovial sarcoma that can aid in its diagnosis." (PMID 32322158, 2020). "Amongst nine cases of synovial sarcoma, TLE1 was positive in seven." (PMID 33061792, 2020). "TLE1 may be of value in the differential diagnosis of synovial sarcoma and should always be used only in the context of a panel of antibodies." (PMID 31893185, 2019). "SS18-SSX/TLE1 proximity ligation signal was detected only in synovial sarcoma samples." (PMID 27120803, 2016). "These were 7 tests for h-caldesmon (for leiomyosarcoma), 3 CDK4 (for WDL/DDL), 2 DOG1 (for GIST), 2 beta-catenin (for fibromatosis), 1 each of CD34 (DFSP), desmin, myogenin (rhabdomyosarcoma (RMS)), p63 (sarcomatoid carcinoma), PSAP (prostatic carcinoma), and TLE1 (synovial sarcoma)." (PMID 25165418, 2014). "Transducin-like enhancer protein 1 (TLE1) is a protein encoded by the TLE1 gene that appears to be a sensitive but not specific marker for synovial sarcoma." (PMID 23691400, 2013). "Transducer-like enhancer of split 1 (TLE1) has been recently described as a novel marker for synovial sarcoma (SS)." (PMID 31938642, 2019). "While the cytokeratin expression in small cell synovial sarcoma can be variable, its presence can still be helpful in a synovial sarcoma diagnosis when interpreted in conjunction with other markers like CD99 and TLE1." (PMID 40861426, 2025). "Immunohistochemical examination and CD99, TLE1, and BCL2 results were positive, so the diagnosis of synovial sarcoma was confirmed." (PMID 39015801, 2024). "The patient has positive expression of TLE-1, Calponin, and EMA, supporting the diagnosis of synovial sarcoma." (PMID 39162837, 2024). "The open biopsy confirmed a spindle mesenchymal tumor with positive immunohistochemistry for CD99 (focal membrane staining), TLE-1 (nuclear staining), and BCL-2 (cytoplasmic staining), consistent with mediastinal synovial sarcoma." (PMID 39015801, 2024). "Synovial sarcoma is positive for CD99, TLE1, focally AE1/AE3, and EMA, and has a characteristic SS18-SSX gene fusion." (PMID 37735390, 2023). "In this case, TLE-1 and SS18-SSX were positive on immunohistochemical analysis, and synovial sarcoma was diagnosed by biomolecular assessment and genetic identification of SS18 by FISH." (PMID 34669095, 2021). "In two cases of poorly differentiated synovial sarcoma with round cell morphology, the diagnosis was made based on positive SS18-SSX1/2 fusion transcripts, and two cases were also positive for TLE1." (PMID 33061792, 2020). "Ossifying synovial sarcomas demonstrate uniform spindle tumor cells and are positive for cytokeratin, EMA, and TLE1 and reveal t(X;18) with SSX2 involvement." (PMID 32867125, 2020). "HDAC inhibitors have been shown to disrupt the SS18-SSX/TLE1/ATF2 protein complex, providing an explanation for the sensitivity of synovial sarcoma cells to HDAC inhibition." (PMID 28056055, 2017). "The SS18-SSX/TLE1/ATF2 protein complex has been shown to be disrupted following treatment with HDAC inhibitors, providing an explanation for the sensitivity of synovial sarcoma cells to HDAC inhibition." (PMID 27120803, 2016). "Co-immunoprecipitation analyses further demonstrate that the interaction of SS18-SSX with TLE1 is specific to synovial sarcoma, as SS18-SSX is pulled down with TLE1 exclusively in synovial sarcoma cell lines." (PMID 27120803, 2016). "Immunohistochemical staining in synovial sarcoma patient surgical specimens demonstrated the presence of SS18-SSX and TLE1 as well as the specificity of TLE1 for synovial sarcoma cells." (PMID 27120803, 2016). "Immunohistochemical markers like TLE1, BCL2, and CD56 are used to diagnose synovial sarcoma." (PMID 40747128, 2025).
synovial sarcoma (continued). "Additionally, synovial sarcomas demonstrate a FISH- or RT-PCR–detectable translocation of t(X;18)(p11;q11), leading to the fusion of SS18 and SSX1 and strong/diffuse TLE1 expression, which can be determined via immunohistochemistry." (PMID 37510144, 2023). "In the case of RANBP2, there are small yet distinct individual cells scattered throughout the field whereas in the case of TLE1, the entire field of vision is covered with positive cells (results not shown), similar to synovial sarcomas." (PMID 35664317, 2022). "The second case with differential diagnosis of solitary fibrous tumor (SFT) and synovial sarcoma was diagnosed as spindle cell rhabdomyosarcoma on morphology and negative TLE1 immunohistochemistry." (PMID 33061792, 2020). "Synovial sarcomas demonstrate strong and diffuse nuclear expression of TLE1 and SS18-SSX and are negative for CD34 and STAT6." (PMID 32867125, 2020). "In our study, we found Transducin-like enhancer of split 1 (TLE1) immunostain as a highly sensitive but not a specific marker for synovial sarcoma (SS)." (PMID 31893185, 2019). "Even though the pathways of TLE1 affecting cancer growth are not clear, our data reflect that the strong sex difference of TLE1 methylation might explain partially that AML and synovial sarcoma are a little more common in males than females." (PMID 20386599, 2010). "For example, TLE1, a transcriptional repressor essential in hematopoesis, neuronal differentiation and terminal epithelial differentiation, has been shown to contribute to acute myeloid leukemia (AML), synovial sarcoma, and other cancers." (PMID 20386599, 2010). "However, a precise definitive diagnosis of synovial sarcoma was made using ancillary techniques; CD99 and TLE-1 could be detected immunohistochemically to confirm the diagnosis." (PMID 40578241, 2025). "In addition, almost all cases of synovial sarcomas, including poorly differentiated tumors, show strong nuclear expression of TLE1, a marker that is not present in EFT." (PMID 40950824, 2025). "Aside from SS18-SSX, high levels of the transcriptional corepressor named Transducin-like Enhancer of Split 1 (TLE1) is specifically found in most, if not all, of synovial sarcoma tumors and is thereby used as an additional way to indicate the presence of synovial sarcoma in the clinic." (PMID 40296913, 2025). "Although TLE1 is diagnostically useful, it is not totally specific for synovial sarcoma." (PMID 32867125, 2020). "Transducin-like enhancer of split 1 (TLE1) may be a reliable immunostain for diagnosing synovial sarcoma (SS) due to its sensitivity, but its expression is not limited to SS as its presence in a number of soft tissue tumors has been established." (PMID 31893185, 2019). "Result came with the finding of tumor being diffusely positive for TLE1, CD56, and BCL2 and negative for STAT6, CD34, and Desmin, suggestive of synovial sarcoma." (PMID 40747128, 2025). "In contrast to biphasic synovial sarcoma, the entrapped alveolar glands show consistent pneumocytic phenotype, which is not the case in synovial sarcoma glands (the latter are CK7+, TLE1+, TTF1-, NapsinA-)." (PMID 32193604, 2020). "Therefore, although the “gold standard” for synovial sarcoma is molecular testing, TLE1-targeted therapeutics could be used to selectively treat synovial sarcoma without damaging host tissue and could be a useful immunohistochemical marker in combination with CD37, CK7, EMA, BCL2, and MIC2." (PMID 27852056, 2017). "No expression of Desmin, SMA, CD31, Caldesmon, TLE-1, WT-1, and SS18 was in the tumor, which could be differentiated from synovial sarcoma." (PMID 40831926, 2025). "In our case, immunohistochemistry confirmed the diagnosis of monophasic synovial sarcoma, with the tumor cells being non-reactive for S-100, Smooth Muscle Actin (SMA), and neurofilament, but positive for TLE1, BCL2, and CD99, which are indicative of this type of sarcoma." (PMID 39364429, 2024).
synovial sarcoma (continued). "However, TLE1 expression was by no means specific for BCS, being present in Ewing-like sarcoma (9/15, 60%), Ewing sarcoma (3/7, 43%), malignant peripheral nerve sheath tumors (2/2, 100%) and synovial sarcoma (4/5, 80%)." (PMID 34103053, 2021).
sarcoma (18 papers, 2016 to 2025). A usually aggressive malignant neoplasm of the soft tissue or bone. "Other diagnostic considerations would include biphasic sarcomas like glandular malignant peripheral nerve sheath tumor (MPNST), especially since TLE-1 can be expressed in MPNST, albeit in a weak fashion." (PMID 40416104, 2025). "The neuroendocrine tumor was positive for chromogranin and synaptophysin; GIST showed immunopositivity for CD117 and SMA; Synovial sarcoma showed immunoexpression of panCK, Bcl2 and TLE1; and epithelioid angiomyolipoma was positive for vimentin, CK7 and HMB45." (PMID 38235567, 2024). "TLE1 has been regarded as a highly sensitive and relatively specific marker of synovia sarcomas with strong and diffuse positive immunoreactivity." (PMID 35639915, 2022). "A comparison of TLE1 expression in other sarcomas would provide much greater insight into establishing the specificity of this robust marker." (PMID 31938642, 2019). "We extracted the expression profiles of four sarcoma-related tumor biomarkers, MDM2, CDK4, CD34, and TLE1, from the cohorts TCGA-SARC and GSE21050 and analyzed their expression profile in each IMS." (PMID 36153483, 2022). "PPSS expresses tumor markers such as transducin-like enhancer of split-1 (TLE1) and B-cell lymphoma 2 (Bcl-2), which can differentiate PPSS from other sarcomas, highlighting the importance of immunohistochemical (IHC) investigations as an important tool to rule out other sarcomas." (PMID 40718269, 2025). "Tumor histology may show a similar appearance to PSS, so to differentiate PSS from other sarcomas, the immunohistochemistry for vimentin, BCL-2, CD99, and TLE1 are common positive markers." (PMID 37170363, 2023). "Of note, CIC-DUX4 translocation sarcomas have been reported to show WT1 staining in >90%, while BCOR-translocation sarcomas were reported to show strong staining of BCOR, BCL-2, cyclinD1, and TLE1 staining in most cases (each 80–90%)." (PMID 32204536, 2020). "Although some SFTs showed weak positivity for TLE1, none of the nonsynovial sarcomas were moderately or strongly reactive for this marker." (PMID 27401493, 2016). "In the 39 nonsynovial sarcoma samples, 94.9 % (37/39) were completely negative for TLE1, whereas only two SFTs showed “1+” staining." (PMID 27401493, 2016). "However, TLE1 is not entirely specific, as it can be positive in other sarcomas, reinforcing the need for confirmatory molecular testing." (PMID 41246769, 2025). "We mapped CTAG1B/A protein to sarcoma transcription pathways with gene set expression analysis (GSEA) and using independent samples, we immunohistochemically identified expression of at least two network neighbors, RANBP2, and TLE1, thus validating our approach." (PMID 35664317, 2022). "Although TLE1 is reported to show strong and diffuse nuclear staining in SS, the specificity of TLE1 IHC for the diagnosis of SS is low because of its positivity in up to one-third of non-SS sarcomas." (PMID 34127031, 2021). "Cyclin D1, SATB2, TLE1, and CD10 are other immunostains that are not specific but helpful in considering a BCOR rearranged sarcoma, as noted in Cases 1 and 3 in this series." (PMID 40705064, 2025).
lung carcinoma (13 papers, 2014 to 2023). "As a critical molecular event underlying lung cancer cell anoikis resistance, the TLE1-mediated repression of E-cadherin acted as a downstream target of the anoikis function of the tumor suppressor Bcl-2 inhibitor of transcription 1 (Bit1)." (PMID 29069783, 2017). "Although the Bit1 inhibition of EMT has been associated with the attenuation of the TLE1-mediated E-cadherin repression, the downstream signaling mechanism underlying Bit1 anoikis function in lung cancer cells remains to be fully delineated." (PMID 29069783, 2017). "For instance, TLE1 was overexpressed in a significant number of human lung cancer tissues and was implicated to be a putative lung specific oncogene in a transgenic mice model." (PMID 26701208, 2016). "Based on the previous finding demonstrating the unique correlation of the transcription factor Zeb1 with loss of E-cadherin expression in human lung cancer cell lines, here we only examined the role of Zeb1 on the observed TLE1-mediated E-cadherin repression." (PMID 27655370, 2016). "Our findings also indicate that a potential mechanism underlying the TLE1 oncogenic function is to protect lung cancer cells from Bit1 induced anoikis." (PMID 25003198, 2014). "Additionally, TLE1 is associated with many cancers in humans, including synovial carcinoma, lung cancer, breast cancer, glioblastoma, gastric cancer, and pancreatic cancer." (PMID 36542663, 2022). "During lung cancer progression and metastatic disease, loss or inactivation of Bit1 function may yield to heightened TLE1 repression of E-cadherin." (PMID 27655370, 2016). "In the case of TLE1-mediated E-cadherin repression in NSCLC cells, Zeb1, an EMT promoting factor uniquely correlated with the loss of E-cadherin expression in human lung cancer cell lines, may, in part, underlie TLE1 recruitment to the E-cadherin promoter." (PMID 27655370, 2016). "Concluding our investigation, qRT-PCR experiments confirmed the heightened expression levels of EPHX1, LDHA, SHC1, MYO6, and TLE1 in lung cancer cell lines." (PMID 37965333, 2023). "TLE1 transgenic mice were reported to spontaneously develop lung cancer, likely due to enhanced ERBB1 and ERBB2 expression." (PMID 36438567, 2022). "These collective results suggest that TLE1 is an effector of anchorage-independent growth of lung cancer cells, at least in part, through the transcription factor ZEB1." (PMID 29069783, 2017). "These collective findings suggest that TLE1 represses E-cadherin expression and promotes anoikis resistance in lung cancer cells." (PMID 29069783, 2017). "Based on numerous studies indicating that an EMT phenotype and particularly the loss of E-cadherin expression is associated with cell survival, we investigated here the role of TLE1 as an effector of anoikis resistance in lung cancer cells." (PMID 29069783, 2017). "Considering that anoikis resistance is a hallmark of EMT and that loss of E-cadherin expression circumvents anoikis, we investigated the role of TLE1 in the anoikis induction in lung cancer cells." (PMID 29069783, 2017). "In summary, the findings presented here have identified the ZEB1/TLE1 as a new transcriptional mechanism in the suppression of E-cadherin in lung cancer cells." (PMID 29069783, 2017). "Our results suggest that TLE1 induces anoikis insensitivity in lung cancer cells by repressing E-cadherin expression, at least in part, via the EMT transcription factor ZEB1." (PMID 29069783, 2017). "It will be interesting to determine if TLE1 functions independently from or synergistically with CtBP to effect full ZEB1-dependent repression of E-cadherin in lung cancer cells." (PMID 29069783, 2017). "Here, we propose a model wherein TLE1 promotes tumorigenicity of lung cancer cells via induction of anoikis resistance through attenuation of the expression of the tumor suppressor gene E-cadherin." (PMID 29069783, 2017).
lung carcinoma (continued). "In this report, we provide evidence that E-cadherin is a novel target of TLE1 in effecting anoikis resistance and its direct transcriptional repression by TLE1 was sufficient to attenuate anoikis sensitivity of lung cancer cells." (PMID 29069783, 2017). "TLE1 overexpression stimulated anchorage-independent growth in chicken embryo fibroblast and promoted epithelial-mesenchymal transition in lung cancer cells." (PMID 26701208, 2016). "We recently demonstrated that the Groucho TLE1 is a novel corepressor which represses E-cadherin in lung cancer cells, in part by recruiting HDAC1 to the E-cadherin promoter." (PMID 27655370, 2016). "The findings of this study provide the first evidence in support of Bit1 as a potential tumor suppressor in human lung cancer and raise the possibility that the previously reported oncogenic function of TLE1 is to attenuate the Bit1 anoikis pathway." (PMID 25003198, 2014). "Consistent with its lung oncogenic function, TLE1 was found to be upregulated in a significant fraction of human lung carcinomas." (PMID 25003198, 2014). "It is interesting to note that disruption of the Bit1 pathway can also be achieved via overexpression of its inhibitor TLE1, which has been shown to be upregulated in human lung cancer." (PMID 25003198, 2014). "In addition, TLE1 overexpression was reported to induce apoptosis resistance and promote anchorage-independent growth in breast and lung cancer cells." (PMID 36438567, 2022). "TLE1 promoted EMT in A549 lung cancer cells via suppressing E‐cadherin." (PMID 33098370, 2020). "Since anoikis resistance is an essential requirement for anchorage-independent growth, a parameter associated with malignant transformation, we then examined whether TLE1 can drive the anchorage-independent growth of lung cancer cells." (PMID 29069783, 2017). "Hence, specific inhibition of the ZEB1/TLE1 nuclear pathway is a viable therapeutic strategy to circumvent lung cancer disease initiation and progression." (PMID 29069783, 2017). "The ZEB1/TLE1-mediated suppression of E-cadherin expression may represent a new pathway utilized by lung cancer cells to acquire anoikis resistance and anchorage-independent growth in vitro, and tumorigenicity in vivo." (PMID 29069783, 2017). "Our collective findings highlight the Bit1/AES/TLE1 pathway as an important determinant of lung cancer progression, and hence its downregulation and/or inactivation may contribute to lung cancer aggressiveness and metastasis." (PMID 27655370, 2016). "In addition, TLE1 was overexpressed in a significant number of human lung cancer tissues, including squamous cell carcinomas and adenocarcinomas." (PMID 26701208, 2016). "Ectopic expression of TLE1 promoted EMT by suppressing E-cadherin in lung cancer cells." (PMID 26701208, 2016). "In contrast, the expression of N-cadherin did not play any relevant influence on the clinical outcome and it is not even important in MTCS development in at least some cancer cell lines as in LLC1 Lewis lung cancer cells, and in A549 lung cancer cells upon exogenous expression of TLE1." (PMID 25756965, 2015). "Considering that anchorage-independent potential is a determinant of transformation and tumorigenesis, the ability of TLE1 to block the Bit1 anoikis pathway may contribute to its oncogenic function in lung carcinoma." (PMID 25003198, 2014). "In this report, we show that TLE1 functions to protect lung cancer cells from Bit1-induced anoikis." (PMID 25003198, 2014). "It has been previously shown that the nuclear TLE1 corepressor is a putative oncogene in lung cancer, and we show here that TLE1 blocks Bit1 mediated anoikis in part by sequestering the pro-apoptotic partner of Bit1, the Amino-terminal Enhancer of Split (AES) protein, in the nucleus." (PMID 25003198, 2014). "The Tle1 transgene caused spontaneous lung cancer, although no test was performed to determine whether this effect was related to Notch overactivation." (PMID 36438567, 2022).